SHISA7 (shisa family member 7)
Description:
Transmembrane protein that regulates gamma-aminobutyric acid type A receptor (GABA(A)R) trafficking, channel deactivation kinetics and pharmacology, necessary for fast inhibitory transmission in the brain. Enhances the action of benzodiazepine, a primary GABA(A)Rs target drug, in the brain. May affect channel kinetics of AMPA-type glutamate receptors (AMPAR), the brain's main excitatory neurotransmitter, necessary for synaptic hippocampal plasticity, and memory recall. May regulate the induction and maintenance of long-term potentiation at Schaffer collaterals/CA3-CA1 excitatory synapses.
Synonyms: CKAMP59
Tractability: Antibody: UniProt predicts a signal peptide or a membrane-spanning region; its Gene Ontology location is reachable by antibodies, with medium confidence. PROTAC: its protein half-life has been measured.
Gene: Protein-coding gene on chromosome 19 (55,428,740 to 55,443,300, reverse strand). Ensembl gene ENSG00000187902.
Subcellular location: Postsynaptic density membrane
Subcellular location (Human Protein Atlas): Cytosol
Gene Ontology:
Molecular function: GABA receptor binding; ionotropic glutamate receptor binding
Biological process: gamma-aminobutyric acid receptor clustering; gamma-aminobutyric acid signaling pathway; memory; positive regulation of long-term synaptic potentiation; regulation of AMPA glutamate receptor clustering; regulation of AMPA receptor activity; regulation of GABA-A receptor activity
Cellular component: AMPA glutamate receptor complex; asymmetric, glutamatergic, excitatory synapse; dendritic spine membrane; glutamatergic synapse; postsynaptic density; postsynaptic density membrane; postsynaptic membrane; postsynaptic specialization membrane
Genetic constraint (gnomAD): Loss-of-function variants: 8 observed, 16.91 expected, observed/expected ratio (o/e) 0.47, 90% interval 0.28 to 0.85. The synonymous counts are far from expectation, so gnomAD's model fits this gene poorly and the ratio says little. Missense variants: 671 observed, 540.25 expected, observed/expected ratio (o/e) 1.24, 90% interval 1.16 to 1.32. Synonymous variants: 386 observed, 271.56 expected, observed/expected ratio (o/e) 1.42, 90% interval 1.31 to 1.55.
Homologues: Orthologues: macaque SHISA7 (99% identical), pig SHISA7 (94% identical), dog SHISA7 (93% identical), mouse Shisa7 (93% identical), rat Shisa7 (93% identical), guinea pig SHISA7 (60% identical), chimpanzee SHISA7 (51% identical), tropical clawed frog shisa7 (46% identical), zebrafish shisa7b (39% identical), zebrafish shisa7a (24% identical). Paralogues in human: SHISA6 (29% identical), SHISA9 (21% identical), SHISA8 (19% identical).
Diseases named in the same sentence as SHISA7 in open-access papers:
SHISA7 is named in the same sentence as 7 diseases in open-access papers, as found by Europe PMC text mining. Sharing a sentence is not in itself a finding about the gene and the disease. The quoted sentences say what the papers report.
alopecia (1 paper, 2022). Hair loss usually from the scalp. "In the top 10 up-regulated DEGs, SHISA7 (shisa family member 7) and ASCL5 (achaete-scute family bHLH transcription factor 5) were 10 and sixfold higher in alopecia males than normal males, respectively." (PMID 35413801, 2022).
Anxiety (1 paper, 2017). Intense feelings of nervousness, tension, or panic often arise in response to interpersonal stresses. "In line with this, Shisa7 KO mice showed a specific deficit in contextual fear memory, both short-term and long-term after conditioning, whereas auditory fear memory and anxiety-related behavior were normal." (PMID 29199957, 2017). "Finally, Shisa7 KO mice were tested in several anxiety-related tasks, such as open field, elevated plus maze and dark-light box, in which no significant genotype effect was observed." (PMID 29199957, 2017).
neuroblastoma (1 paper, 2022). Neuroblastoma (NB) is the most common solid, extracranial childhood tumor. "As previously stated, recent research using human neuroblastoma cell lines found that hsa-miR-185-5p regulates BCAS4 and SHISA7 in a ceRNA manner, which is consistent with our findings." (PMID 35264942, 2022). "In line with our results, a prior study on a human neuroblastoma cell line found that ceRNA regulation between BCAS4 and SHISA7 by hsa-miR-185-5p is conserved in humans." (PMID 35264942, 2022).
prion disease (1 paper, 2026). A transmissible disease that is caused by a protein that is able to induce abnormal folding of normal cellular proteins, leading to characteristic spongiform brain changes, which are associated with neuronal loss without an inflammatory response. "RNA-seq analysis revealed that hypothalamic CYTB, ATP6, COX, ABLIM1, and ABI3 were significantly upregulated in IM group, whereas SHISA7 and PTPRO were significantly downregulated, with notable enrichment in prion disease, oxidative phosphorylation, and thermogenesis pathways." (PMID 41715947, 2026).
tumor (1 paper, 2020). "By comparing with the normal group, we found that apolipoprotein B (APOB) and carbonic anhydrase 1 (CA1) were significantly up-regulated, whereas angiopoietin like 5 (ANGPTL5) and shisa family member 7 (SHISA7) were down-regulated in the tumor samples." (PMID 33050883, 2020).
SHISA7 also shares sentences with these, for which no sentence is quoted: Alzheimer disease (1 paper); neurodevelopmental disorder (1).